CD28 (CD28 molecule)
Diseases named in the same sentence as CD28 in open-access papers (continued):
Sharing a sentence is not in itself a finding about the gene and the disease.
infection (continued). "The mRNA expression levels of CD80, CD274, and CD28 in the liver were increased at 6 w after infection, which was consistent with the sequencing results." (PMID 39590301, 2024). "In contrast, after restimulation with anti-CD3 and anti-CD28 mAbs, infection-induced mouse MLN cells secreted low levels of Th1 cell cytokines IL-2 and IFN-γ." (PMID 38166140, 2024). "In the present study, we discovered the occurrence of significantly increased expressions of CD28 on CD8+ T cells in T. gondii-infected ICOS−/− mice when compared to infected WT mice during the chronic stage of the infection." (PMID 39682747, 2024). "Previous studies, conducted using infections with vaccinia virus, influenza virus, and Listeria monocytogenes, demonstrated the requirement of CD28 for optimal recall responses of CD8+ T cells." (PMID 39682747, 2024). "Restimulation of mesenteric lymph node (mLN) cells 21 days post-infection (p.i.)with anti-CD3/CD28 induces the production of type-2 cytokines, such as IL-4, IL-5, and IL-13, in cells derived from WT mice but not in A20myel-KO mLN cells." (PMID 38680500, 2024). "It is unclear why MAdCAM-1 is superior to either VCAM-1 or CD28 Ab with respect to supporting infection." (PMID 36897929, 2023). "Lentiviral transduction of CD3/CD28-activated T cells from human healthy donors was carried out with variable multiplicity of infection (MOI = 1, 2, 5) for 48 h, and untransduced donor T (UTD) cells were used as control." (PMID 37663131, 2023). "Selectively targeting formation of the B7/CD28 costimulatory axis through the receptor homodimer interfaces provides a mechanism for attenuating lethal host inflammatory responses to infections, exemplified here with superantigen-induced toxic shock." (PMID 37381064, 2023). "Within the 1st cohort CD28, a co-stimulatory molecule on T-cells required for T-cell activation, was increased in CS patients during the acute phase of infection." (PMID 37041310, 2023). "In summary, in the chronic phase after TMEV-infection, the deletion of CD28 results in variable outcome." (PMID 37090733, 2023). "This strongly supports the concept that B7/CD28 signaling is broadly involved in the inflammatory pathogenesis of different infections." (PMID 37381064, 2023). "We observed that the frequency of Vhl cKO CD4 T cells after anti-CD3/CD28 stimulation of splenocytes was low, resembling changes in T cell frequencies during infection in vivo." (PMID 36064840, 2022). "To assess the function of these NK cells, we isolated allogeneic CD4+ T cells from the PBMCs of healthy donors and performed CD3 and CD28 co-stimulation for three days prior to infection with 800 ng of p24 of X4-tropic NL4-3 or R5-tropic NFNSX for 24 h." (PMID 35013215, 2022). "To this end, we isolated CD4+ T cells from healthy donors and then transfected them with antagomiR-31 or antagoNC, followed by 72-hr stimulation with anti-CD3/CD28 antibodies before infection with HIV-1 at a multiplicity of infection (MOI) of 0.01." (PMID 34804062, 2021). "Flow cytometric analysis after polyclonal stimulation with anti-CD3/CD28 showed that the H1-DDA/TDB-induced accumulation of IL-17A-producing cells within the CD44+CD4+CD90+ population at week 2 post-infection was highly impaired in IL-23p19−/− mice." (PMID 34351501, 2021). "CD28 expression is required for helper T cell polarization in response to infection, which agrees with our study in which all three knockout mice strains lack CD28 signaling." (PMID 34281386, 2021). "In this model of latency, we had previously observed that the degree of infection on day 13 was correlated with the degree of reactivation seen on day 19 with CD3/CD28 beads." (PMID 33441346, 2021). "CD4+ T cells were either unstimulated or activated with anti-CD3/anti-CD28 beads prior to infection with HIV-1VSVgNL4-3, whereas monocyte derived macrophages (MDMs) were infected with R5-tropic HIV-1NL4-3 BaL." (PMID 34962974, 2021).
infection (continued). "Cultures were grown for ∼2 mo in the presence of IL-2 with periodic CD3/CD28 reactivation, while monitoring for activation markers and frequency of infection." (PMID 33318172, 2020). "MHC-I levels were higher in the presence of PKCa or aCD3/CD28 on the day of infection and decreased over 72 hours back to control levels." (PMID 32196533, 2020). "Both vaccine groups also showed a significant increase in the frequency of the SIV-specific memory T cell subset with cytotoxic potential (CD95+ CD28− GrzB+) (P = 0.007 and P = 0.005, respectively) upon infection." (PMID 29793957, 2018). "At 4 days post-infection, csGFP- were sorted, cultured overnight and stimulated with αCD3/CD28 in presence of raltegravir." (PMID 29714165, 2018). "Briefly, CD4+ T-cells were purified from blood of four healthy donors and activated for 72 hr with αCD3/CD28 beads and 20 U/ml IL-2 before infection with HIVGKO." (PMID 29714165, 2018). "CD4+ T cells were stimulated with anti-CD3/CD28 antibodies in a limiting dilution format in the presence of raltegravir, to avoid new rounds of infection." (PMID 30316868, 2018). "HIV-1 has evolved multiple means of downregulating CD28, which are in part genetically separable from CD4 and MHC-I downregulation, implying that CD28 downregulation is critical during infection." (PMID 29329537, 2018). "In fact, the expansion of CD4+CD28- T cells in GPA is suggested to be driven by CMV infections, and is associated with increased risk of infection and mortality." (PMID 28615072, 2017). "Infection with HIV significantly reduced anti-CD3/anti-CD28-induced secretion of IL-17 by blood-derived (p < 0.001) and in vitro-generated (p = 0.046) Th17 cells." (PMID 29091911, 2017). "CD4+ T cells were isolated from the peripheral blood mononuclear cells (PBMCs) of healthy donors and then activated with anti-CD3 and anti-CD28 before infection." (PMID 27145859, 2016). "Timing of stimulation with anti-CD3/CD28 mAb and infection with SeV vectors were found to be critical in reprogramming TILs." (PMID 27057178, 2016). "We have analyzed transduction efficiencies (multiplicity of infection (m.o.i.)= 1) following stimulation of naïve T cells for 48 h with magnetic anti-CD3/CD28 beads and IL-7, IL-15 and IL-21." (PMID 27435312, 2016). "In this study, BVDV promoted the upregulation of CD28 mRNA and protein expression during the initial stage of infection." (PMID 27617959, 2016). "Compared with the OVA-specific memory CD8+ T cells from Wt donors, we observed that memory T cells from Cd28−/− or Ox40−/− donors had significantly reduced upregulation in the mRNA expression of c-Myc and Nfkb1 at day 35 post-infection of VV-OVA." (PMID 26791245, 2016). "In fact, CD28 knockout mice infected with Plasmodium chabaudi were unable to resolve the infection, maintaining low levels of parasitaemia for weeks after infection." (PMID 27255376, 2016). "The essential function of CD28 for conferring host protection during secondary infection has been confirmed using the cre-lox system allowing a CD28-inducible KO in a model of infection by N. Brasiliensis." (PMID 26322044, 2015). "At 6 days after infection, similar levels of CD28 were observed on CD4+ T cells and TFH cells from old and adult mice, suggesting that decreased expression of co-stimulatory molecules was not responsible for the delayed germinal center development in old mice." (PMID 26204259, 2015). "In agreement with Brégnard, we and others have previously demonstrated that HIV can become directly silenced following infection events as evidenced by enhancement of frequency of EGFP(+) cells following stimulation with anti-CD3/CD28, SAHA, or TNF-α." (PMID 26559763, 2015). "Taken together, these data suggest that abrogating CD28 costimulation impairs production of host protective Th2 cytokines during N. brasiliensis secondary infection." (PMID 24516382, 2014).
infection (continued). "Total MLN cells re-stimulated with α-CD3 resulted in significantly reduced production of IL-13 by CD28−/− mice at day 9 post-infection and was similar at day 12 compared to wild-type mice, a cytokine crucial for worm clearance." (PMID 24516382, 2014). "The contribution of CD28 costimulation during recall of memory responses to infections has remained controversial despite numerous attempts to study it." (PMID 24516382, 2014). "Together, these data demonstrated that CD28 is required for optimal immunity against N. brasiliensis primary infection." (PMID 24516382, 2014). "These CD28 dependent interactions are important during the initiation of T cell mediated immunity against a number of infections." (PMID 24516382, 2014). "Histological examination of periodic-acid Schiff (PAS) stained intestinal sections further confirmed that infected CD28−/− mice had impaired goblet cell hyperplasia at day 9 post-infection compared to infected C57BL/6 mice." (PMID 24516382, 2014). "Maintained CD28 expression is also required for clearance of the enteropathic bacteria C. rodentium after oral infection." (PMID 25347065, 2014). "In summary, CD28 is crucial for protection against N. brasiliensis secondary infection and plays a key role in the recruitment of TFH cells, memory CD4+ T cells and follicular B cells." (PMID 24516382, 2014). "Following primary infection with N. brasiliensis, CD28−/− mice had delayed expulsion of adult worms in the small intestine compared to wild-type C57BL/6 mice that cleared the infection by day 9 post-infection." (PMID 24516382, 2014). "CD28 costimulation seems to be required throughout the infection period to sustain the development of protective memory responses." (PMID 24516382, 2014). "Infected CD28−/− mice had significantly higher intestinal adult worm burdens at day 9 post-infection compared to infected wild-type C57BL/6 mice." (PMID 24516382, 2014). "Associated with transiently increased worm burdens in infected CD28−/− mice was the number of mucus producing goblet cells that were reduced at day 9 post-infection in this mouse strain compared to control mice." (PMID 24516382, 2014). "This has been further confirmed by other studies that have demonstrated that interfering with CD28 costimulation during primary infection with nematodes impairs optimal development of Th2 cytokine responses." (PMID 24516382, 2014). "This demonstrates that CD28 expression is required after T cell priming for intact effector CD4+ T cell responses during infection." (PMID 25347065, 2014). "Taken together, this illustrates that CD28 is a critical co-stimulatory molecule throughout the effector phase of the response to infection, which has significant implications for applied immunology." (PMID 25347065, 2014). "The authors show that deletion of CD28, after clearance of the first infection and prior to re-infection, resulted in fewer Th2 cells and Tfh cells forming in response to secondary infection." (PMID 25347065, 2014). "The requirement of CD28 costimulatory signalling during recall of memory responses against infections has remained controversial." (PMID 24516382, 2014). "Together, this study demonstrates that CD28 persistence is required for helper T cell polarization in response to infection, describing a novel function for CD28 that is distinct from its role in T cell priming." (PMID 25347065, 2014). "The results presented here demonstrate that continued CD28 signaling is required following T cell activation for an effective primary CD4+ T cell response to infection." (PMID 25347065, 2014). "Primary CD3/CD28 activated CD4+ T cells were infected with HTLV-1 in a dose dependent manner using an in vitro trans-infection system in which CD4+ T cells were co-cultured with HTLV-1 shedding MT-2 cells." (PMID 25521510, 2014). "We activated a subset of cells with anti-CD3/CD28 beads 2 days after infection in order to compare receptor expression on infected resting vs. activated cells." (PMID 25330112, 2014).
infection (continued). "In our present study, we expected an accumulation of CD57+CD28− T cells in the adolescents with longer duration of infection." (PMID 23029209, 2012). "Our findings indicate that CNS TB in pediatric patients increases the sensitivity of CD4 and CD8+/CD28+ T cells to apoptosis, suggesting a hypoergic status of this infection." (PMID 22111973, 2011). "Untransfected cells or cells transfected with 10 pmol control siRNA or PAK2 targeting siRNA were infected with VSV-G pseudotyped HIV expressing the indicated Nef and then stimulated 24 h post-infection with α-CD3/CD28 beads for 4 h." (PMID 21819585, 2011). "Presence of MICA in the tracheal epithelial cells and the reduced levels of CD28 in effector CD8+ T cells suggest an essential co-stimulatory role for NKG2D at the site of infection." (PMID 20844584, 2010). "Efficient infection of mouse T cells required continued activation of the TCR with anti-CD3/CD28, particularly for the 12–20 hour period after infection." (PMID 18237418, 2008). "As infection with CMV is associated with functional and phenotypic changes in T cells such as loss of CD28 expression and terminal differentiation, the proportion of Malawians and UK adolescents who were CMV seropositive was assessed." (PMID 18922182, 2008). "In mice, we confirmed that CD28-knockout (CD28ko) animals on the C57BL/6 (B6) background are susceptible to cutaneous infection with mouse papillomavirus (MmuPV1); however, their skin warts regressed spontaneously approximately five weeks post-infection." (PMID 41805718, 2026). "We established a nomogram based on the T-cell count, CD28+CD8+ T-cell count, CD38+CD8+ T-cell count and clinical risk factors that can help clinical physicians quickly rule out IAC or identify elderly patients at greater risk for IAC at the onset of infection." (PMID 39726780, 2024). "In the acute phase at 14 days post TMEV-infection (dpi), both CD28-knockout strains showed virus spread within the central nervous system (CNS) as an uncommon finding in C57BL/6 mice, accompanied by histopathological changes such as reduced microglial activation." (PMID 37090733, 2023). "Due to the detrimental effects of the tamoxifen-induced conditional CD28-knockout in the early phase of TMEV-infection (weight loss, clinical signs), Cre-Tam mice were not included in this part of the study for animal welfare reasons." (PMID 37090733, 2023). "Therefore, the chronic TMEV-infection was only investigated in mice with conventional CD28-knockout (CD28KO)." (PMID 37090733, 2023). "In addition, there was no increase in axonal damage (beta APP positive axons) within the spinal cord of CD28-knockout mice in the early phase of TMEV-infection at 14 dpi." (PMID 37090733, 2023). "Consistently, CD28+/+ and CD28-/- mice were revealed to have equivalent increases in the percentage and quantity of the γδ T cells and IL-17A+/IFNγ+ γδ T cells in a listeria model of Infection." (PMID 35603176, 2022). "The abundance of CD8 + CD28- T cells early in the infection is predictive of progression to AIDS65." (PMID 36307445, 2022). "In some experiments, T cells were also activated by Phorbol myristate acetate (PMA) for 2 h for Jurkat cells or by a combination of IL2 + CD3 + CD28 for 3 days for primary T cells before infection, considering a large proportion of T cells is activated in human." (PMID 35277473, 2022). "Although CD8+ T lymphocytes play an important part in controlling M. leprae proliferation, the presence of these senescent lymphocytes (CD8+CD28−) may hinder the control of infection due to their regulatory T cell activities." (PMID 33777045, 2021). "In contrast, mice deficient in only CD2 or CD28 are not susceptible to spontaneous infection, although CD28-deficient mice can be infected when directly inoculated." (PMID 33669726, 2021). "However, CD28-deficient and CD2/CD28 deficient mice are able to clear infection, although such clearance is delayed." (PMID 33669726, 2021).
infection (continued). "It was reported that T cell memory is independent of CD28, and that CD28-deficient mice showed efficient type 1 and type 2 responses during infection with Leishmania major and Heligmosoides polygyrus, respectively." (PMID 31979279, 2020). "Additionally, compared to SIVmac239-specific CTLs, greater proportions of RhCMV-specific CTLs were of the terminally differentiated effector memory phenotype (CD28– CCR7–) during chronic SIVmac239 infection." (PMID 32922404, 2020). "Following CD3/CD28-mediated activation at 3 days post-infection, numbers of R5 HIV-1+ cells and X4 HIV-1+ cells increased significantly only in the CCR5+ TM subset, suggesting that it provides a major reservoir of replication-competent, latently infected viruses." (PMID 31036079, 2019). "As a positive control, we also examined the infection of PBT stimulated with anti-CD3/CD28 beads." (PMID 31042779, 2019). "Despite their early protective immunity, CD28-sufficient mice showed at the late phase of infection a persistent presence of Treg cells, impaired T cell responses, elevated production of anti-inflammatory cytokines and higher mortality rates when compared with CD28−/- mice." (PMID 30067137, 2019). "This suggests that HIV-1 proteins other than Nef and Vpu may also be contributing to changes in cell surface CD28 levels upon infection." (PMID 29329537, 2018). "Our findings reveal a successful translation of confirmed immunological findings into farm animal breeding: The broad-spectrum, immunity-promoting molecule CD28 combined with the technical use of transgene, produce a farm animal with improved immune responses to vaccination and pathogen infection." (PMID 28955336, 2017). "The frequency of OVA-specific CD8+ T cells in the recipients receiving the T cells from Cd28−/− or Ox40−/− mice was dramatically lower from days 7 to 35 post-infection with VV-OVA in comparison to the recipients receiving the transferred T cells from OT-I mice." (PMID 26791245, 2016). "Although CD28 signaling plays critical role in Tfh differentiation and maintenance, its downstream PI3k activation is dispensable for its generation and during infection with Salmonella in Roquin mutant mice, the generation Tfh does not depend on CD28 signaling." (PMID 27933060, 2016). "Subsequent challenge of high-dose SIVmac251 resulted in infection in all animals; however, the acute phase of infection showed a reduction in viral replication by more than two orders of magnitude and protection against CD4 T cell (CD28+ CD95+) loss." (PMID 27446074, 2016). "Therefore, the co-inhibitory receptor CTLA-4 that binds to B7.1 and B7.2 was blocked with antibodies during infection, which increases the availability of the B7 molecules to stimulate CD28." (PMID 26263500, 2015). "As continued CD28 was dispensable for Th1 maintenance, we investigated whether CD28 signaling was important for Th1 expansion beyond day 5 post infection." (PMID 25347065, 2014). "In order to investigate whether CD28 is required for the development of protective immunity against N. brasiliensis infection, CD28−/− mice were infected with 500 infective N. brasiliensis larvae and killed 9 and 12 days post-infection." (PMID 24516382, 2014). "Mice deficient in CD28 failed to develop adequate Th2 immune response during infection with S. mansoni, L. major and N. brasiliensis." (PMID 24516382, 2014). "Hence, new approaches that don't suffer from these additional effects are required to solve the conundrum surrounding the contribution of CD28 during recall of memory responses to infections." (PMID 24516382, 2014). "Furthermore, infection of CD28−/− mice with fungi B. dermatitidis revealed maintenance of memory T cells is CD28 independent." (PMID 24516382, 2014). "Hence, we concluded that CD28 costimulation is important for development of TFH cells in the reactive lymph nodes during re-infection with the nematode N. brasiliensis." (PMID 24516382, 2014).